FOXD3 (forkhead box D3)
Description:
Binds to the consensus sequence 5'-A[AT]T[AG]TTTGTTT-3' and acts as a transcriptional repressor. Also acts as a transcriptional activator. Negatively regulates transcription of transcriptional repressor RHIT/ZNF205. Promotes development of neural crest cells from neural tube progenitors. Restricts neural progenitor cells to the neural crest lineage while suppressing interneuron differentiation. Required for maintenance of pluripotent cells in the pre-implantation and peri-implantation stages of embryogenesis.
Synonyms: HFH2; Genesis; AIS1; VAMAS2
Tractability: No criterion of Open Targets' tractability assessment is met for any kind of drug.
Gene: Protein-coding gene on chromosome 1 (63,322,567 to 63,325,128, forward strand). Ensembl gene ENSG00000187140.
Subcellular location: Nucleus
Pathways (Reactome):
Developmental Biology: POU5F1 (OCT4), SOX2, NANOG activate genes related to proliferation; Transcriptional and post-translational regulation of MITF-M expression and activity
Gene Ontology:
Molecular function: DNA-binding transcription repressor activity, RNA polymerase II-specific; protein binding; RNA polymerase II transcription regulatory region sequence-specific DNA binding; sequence-specific double-stranded DNA binding; DNA-binding transcription factor activity; DNA-binding transcription factor activity, RNA polymerase II-specific; RNA polymerase II cis-regulatory region sequence-specific DNA binding; sequence-specific DNA binding
Biological process: negative regulation of transcription by RNA polymerase II; positive regulation of transcription by RNA polymerase II; anatomical structure morphogenesis; cell differentiation; in utero embryonic development; regulation of transcription by RNA polymerase II; regulation of DNA-templated transcription
Cellular component: chromatin; nucleoplasm; nucleus
Genetic constraint (gnomAD): Loss-of-function variants: 3 observed, 2.65 expected, observed/expected ratio (o/e) 1.13, 90% interval 0.47 to 1.89. That is too few expected variants to judge how well the gene tolerates losing a copy. Missense variants: 686 observed, 566.27 expected, observed/expected ratio (o/e) 1.21, 90% interval 1.14 to 1.29. Synonymous variants: 391 observed, 278.28 expected, observed/expected ratio (o/e) 1.4, 90% interval 1.29 to 1.53.
Gene-disease validity (ClinGen):
ClinGen rates the evidence that FOXD3 causes each of these diseases.
aniridia (autosomal dominant): Disputed. Aniridia is a congenital ocular malformation characterized by the complete or partial absence of the iris.
Homologues: Orthologues: chimpanzee FOXD3 (99% identical), macaque FOXD3 (99% identical), dog FOXD3 (97% identical), pig FOXD3 (97% identical), mouse Foxd3 (90% identical), rat Foxd3 (90% identical), tropical clawed frog foxd3 (60% identical), zebrafish foxd3 (59% identical). Paralogues in human: FOXD1 (44% identical), FOXD2 (36% identical), FOXD4L1 (27% identical), FOXD4 (26% identical), FOXD4L4 (26% identical), FOXD4L5 (26% identical), FOXD4L6 (26% identical), FOXD4L3 (26% identical), FOXC2 (23% identical), FOXC1 (23% identical), FOXA1 (21% identical), FOXE1 (21% identical), and 29 more.
Diseases named in the same sentence as FOXD3 in open-access papers:
FOXD3 is named in the same sentence as 72 diseases in open-access papers, as found by Europe PMC text mining. Sharing a sentence is not in itself a finding about the gene and the disease. The quoted sentences say what the papers report.
melanoma (45 papers, 2010 to 2025). A malignant, usually aggressive tumor composed of atypical, neoplastic melanocytes. "Furthermore, FOXD3 expression was upregulated when the B-RAF-MEK-ERK1/2 pathway was inhibited in the B-RAF-mutated melanoma cells." (PMID 37151068, 2023). "However, in mutant B-RAF melanoma cells, adaptive upregulation of FOXD3 can cause resistance to PLX4032/4720 (a target therapy regent)-induced cell death." (PMID 27027443, 2016). "In BRAF-mutated melanoma cells, the inhibition of ERK1/2 signaling leads to the induction of forkhead box D3 (FOXD3), which influences the sumoylation of SOX10." (PMID 40872623, 2025). "Forkhead box D3 (FoXD3) is a stem cell/pluripotency transcription factor that can be triggered upon BRAF/MEK pathway inhibition in mutant BRAF melanomas." (PMID 38835349, 2024). "In a converse experiment, we show here that siRNA-mediated MITF silencing in 501mel and SK28 human melanoma cells leads to upregulation of FOXD3." (PMID 34878101, 2022). "It has previously been shown that FOXD3 overexpression in melanoma cell lines or cultured quail neural crest cells resulted in repression of MITF expression." (PMID 34878101, 2022). "It has been shown that FoxD3 represses the expression of mitfa in zebrafish, in melanoma cell lines and in cultured quail neural crest." (PMID 34878101, 2022). "In human melanocytes, MAPK signaling causes reduction of MITF and increases ERBB3, FOXD3 and NRG1 transcription factor gene expression, with NRG1 and FOXD3 also further upregulating ERBB3, which can heterodimerize with EGFR causing melanoma metastasis." (PMID 34067095, 2021). "Further investigations are needed to elucidate the role of this regulatory cross-talk between VISTA and FOXD3 in melanoma biology." (PMID 34093577, 2021). "The shRNA-mediated down regulation of CD133 or CD271 in melanoma cells revealed that both markers are inversely correlated, suggesting that CD133 suppresses genes associated with CD271, e.g., AXL and FOXD3 and vice versa." (PMID 32878000, 2020). "In contrast, adifferent member of the FOX family, the stem cell transcription factor forkheadbox D3 (FOXD3) has been identified as an adaptive mediator of the response toMAPK pathway inhibition selectively in mutant BRAF melanomas." (PMID 29615030, 2018). "In human mutant BRAF melanoma cells, the stemness transcription factor FOXD3 is rapidly induced by inhibition of ERK1/2 signaling and mediates adaptive resistance to RAF inhibitors." (PMID 29295999, 2018). "As an important mediator of adaptive resistance to RAF inhibitors, FOXD3 depletion promotes the cytotoxic effect of RAF inhibitors in mutant BRAF melanoma cells." (PMID 29295999, 2018). "Here we show that SOX10 is both necessary and sufficient for RAF inhibitor-induced expression of FOXD3 in mutant BRAF melanoma cells." (PMID 29295999, 2018). "Our work completes an ERK/SOX10/FOXD3/ERBB3 pathway that governs the FOXD3-mediated adaptive resistance to RAF/MEK inhibitors in mutant BRAF melanoma." (PMID 29295999, 2018). "Expression of WT HA-SOX10 efficiently rescued FOXD3 induction by ERK inhibition in melanoma cells depleted of endogenous SOX10." (PMID 29295999, 2018). "One important mediator of adaptive resistance in mutant BRAF melanoma cells is the lineage-specific transcription factor, FOXD3, which undergoes rapid transcriptional induction upon inhibition of ERK1/2 signaling and activates the ERBB3/PI3K/AKT pathway." (PMID 29295999, 2018). "FOXD3 expression leads to a significant decrease in melanoma cell migration that can be efficiently reversed by the overexpression of TWIST1." (PMID 27926503, 2017). "The previous studies demonstrated that FOXD3 overexpression significantly inhibits cell growth in lung cancer cells and induces a potent G0/G1 arrest in melanoma cells, which is consistent with our results." (PMID 27926503, 2017). "In melanoma cells, ectopic induction of FOXD3 resulted in G1/S phase arrest and suppressed tumor migration and invasion." (PMID 28430585, 2017).
melanoma (continued). "Exploring the mechanism of this switch, Thomas and Erickson (2009) demonstrated that FOXD3, in mouse melanoma cells or in quail neural crest cells, repressed MITF expression even in the presence of PAX3 and SOX10." (PMID 25670789, 2015). "Studies have shown that SOX10 contributes to melanoma’s adaptive resistance to RAF inhibitors via the ERK1/2/SOX10/FOXD3/ERBB3 signaling pathway.The imperative for developing a prognostic model based on SOX10 is to enhance melanoma patients’ survival rates and refine treatment strategies." (PMID 40342816, 2025). "Abnormal FOXD3 expression has been observed in melanomas, neuroblastomas, and other cancers." (PMID 39494294, 2024). "FOXD3 gene could act as a tumor suppressor gene in a variety of tumors, including malignant melanoma, lung cancer, colorectal cancer, liver cancer, breast cancer, and thyroid cancer." (PMID 37151068, 2023). "However, FOXD3, a poor prognosis gene in our model, was reported as a suppressor factor of H pylori infection-induced gastric carcinoma and melanoma." (PMID 36816541, 2023). "In agreement with this hypothesis, constitutive activation of β-catenin in Schwannoma cells led to FOXD3 repression, whereas MITF silencing upregulated FOXD3 expression in melanoma cell lines." (PMID 34878101, 2022). "In contrast, overexpression of FOXD3 in melanoma cell lines represses MITF expression." (PMID 34878101, 2022). "Forkhead box D3 (FOXD3) is a transcription factor that affects the therapy resistance in melanoma." (PMID 34093577, 2021). "Intriguingly, while some NCSC factors, such as SOX10 and YY1, are activated upon melanoma formation and are required for melanoma growth, other NCSC-associated factors, such as CD271/NGFR/p75NTR, PAX3, and FOXD3 promote melanoma cell invasiveness and metastasis formation." (PMID 34417458, 2021). "It has been previously shown that the transcription factor FOXD3 is rapidly induced in melanoma cells upon inhibition of MAPK signalling and that this phenomenon contributes to adaptive resistance to RAF inhibitors also in part through enhanced transcription of the ErbB3 receptor gene." (PMID 31557826, 2019). "Indeed, we identify SOX10 as a novel regulator of FOXD3 in human mutant BRAF melanoma that binds to a conserved regulatory element located 270 bp upstream from the transcription starting site and activates FOXD3 transcription." (PMID 29295999, 2018). "Our findings not only delineate a signaling network that governs the FOXD3-mediated adaptive resistance to RAF inhibitors in mutant BRAF melanoma but also demonstrate an intricate regulatory switch of SOX10 transcription activity that involves interplay between phosphorylation and sumoylation." (PMID 29295999, 2018). "Thus, in addition to the NC1 and NC2 enhancer-mediated regulation of FOXD3, the SOX10/FOXD3 axis discovered in mutant BRAF melanoma cells is likely a new component of the complex regulatory network that controls the development of neural crest." (PMID 29295999, 2018). "We then investigated whether SOX10 is a mediator of the ERK-dependent regulation of FOXD3 in mutant BRAF melanoma cells." (PMID 29295999, 2018). "Thus, our work discovers a novel phosphorylation-dependent regulatory mechanism of SOX10 transcription activity and completes an ERK1/2/SOX10/FOXD3/ERBB3 axis that mediates adaptive resistance to RAF inhibitors in mutant BRAF melanoma cells." (PMID 29295999, 2018).
melanoma (continued). "Although the role of FOXD3 as a mediator of adaptive resistance to RAF inhibitors in mutant BRAF melanoma cells has been well established, how ERK signaling controls FOXD3 expression remains unclear." (PMID 29295999, 2018). "Notably, a positive correlation was also found between SOX10 and FOXD3 in both data sets when analyzing all melanoma genotypes and selectively BRAF mutant melanoma." (PMID 29295999, 2018). "Also, FOXD3 expression in melanoma cells downregulated migration and invasion by inhibiting Rnd3 expression, consistent with our results." (PMID 28430585, 2017). "In melanoma, FOXD3 increases PAX3 expression and contributes to melanoma progression." (PMID 27926503, 2017). "A previous study showed that FOXD3 expression is elevated following the targeted inhibition of the B-RAF-MEK (MAP/ERK kinase)-ERK (extracellular signal-regulated kinase) 1/2 pathway in mutant B-RAF melanoma cells." (PMID 27926503, 2017). "To investigate the role of SOX10, MITF, and FOXD3 and the reported effects due to BRAF status in ERBB3 regulation, we depleted the three former genes individually and in combination for MITF/FOXD3 by the use of siRNA in three melanoma cell lines: WM983B, MeWo and WM115." (PMID 27391157, 2016). "Since FOXD3 exerts inhibiting effects on the initiation and progression of cancer, it is plausible that FOXD3 expression is downregulated in a range of malignancies, including breast, colorectal cancers as well as neuroblastoma, melanoma and chronic lymphocytic leukemia (CLL)." (PMID 26011451, 2015). "Also, FOXD3-dependent upregulation of the EGFR family member ERBB3 was described after BRAF- or MEK inhibition in melanoma cells, resulting in enhanced responsiveness to ERBB3 ligands and the sensitization towards the BRAF inhibitor PLX4720 by lapatinib." (PMID 24970815, 2014). "Moreover, MITF binds to regulatory elements at the FOXD3 locus in human melanoma cells and primary melanocytes and may therefore directly inhibit its expression." (PMID 34878101, 2022). "We analyzed whether there is a regulatory relationship between SOX10 and FOXD3 in melanoma cells." (PMID 29295999, 2018). "SOX10 promotes the proliferation and growth of melanoma, activating specific targets such as MIT, long non-coding RNA (Inc RNA), SAMMSON, and FOXD3." (PMID 40872623, 2025). "GDF6 developed a neural crest genetic fingerprint in A375 melanoma cell lines, and upregulated the NC markers SOX10, FOXD3, and SNAI2 while downregulating the growth inhibiting SOX9 protein." (PMID 38426087, 2024). "In melanoma, the inhibition of BRAF promotes the upregulation of FOXD3 (factor Forkhead box D3) by blocking MEK/ERK." (PMID 35831836, 2022). "FOXD3 is then able to directly activate the expression of ERBB3 at the transcriptional level, enhancing the responsiveness of melanoma cells to NRG1 (the ligand for ERBB3), and thus leading to the reactivation of both MAPK and PI3K/AKT pathways." (PMID 33507915, 2021). "For instance, the transcription factors PAX3, FOXD3, and SOX10 are part of a gene regulatory network in early NC development that also supports melanoma cell growth, migration, and resistance to targeted therapy, respectively." (PMID 34417458, 2021). "Interestingly our data confirm in all BRAF mutated melanoma cell lines analysed that FOXD3 mRNA is upregulated, however it never precedes temporally upregulation of NRG1, which, to our opinion, remains therefore the principal driver of adaptive resistance to BRAF and MEK inhibitors." (PMID 31557826, 2019). "Here, the authors show that ERK1/2 mediated phosphorylation regulates sumoylation of SOX10 which activates FOXD3, and depletion of SOX10 sensitises BRAF mutant melanoma cells to RAF inhibitors." (PMID 29295999, 2018). "This SOX10-dependent induction of FOXD3 by inhibition of ERK1/2 signaling is durable for at least 120 h and is also present in melanoma cells treated with a combination of RAF and MEK inhibitors." (PMID 29295999, 2018).
melanoma (continued). "In contrast, FOXD3 overexpression inhibits the migration, invasion, and spheroid outgrowth of mutant B-RAF melanoma cells." (PMID 27926503, 2017). "To investigate the relationship between SOX10, MITF, FOXD3, ERBB3 and NRG1 in patient samples, we utilized The Cancer Genome Atlas (TCGA, SKCM), which contains a set of 474 melanoma patient samples." (PMID 27391157, 2016). "We compared basal mRNA expression levels of SOX10, MITF, FOXD3, and ERBB3 in immortalized melanocytes, and in a panel of melanomas spanning various genetic backgrounds." (PMID 27391157, 2016). "In this context, it is intriguing that in melanoma cells, BRAF suppresses FOXD3, which would allow MITF expression to prevail." (PMID 25818589, 2015). "Additionally, NOTCH, WNT, and SOX family members, as well as MITF, Paired Box 3 (PAX3), and Forkhead Box D3 (FOXD3) are essential for early neural crest development and have been reviewed in the context of initiating EMT in melanoma." (PMID 38426087, 2024). "FoXD3, a transcription factor of HER3, can upregulate HER3 and increase the resistance to rapidly accelerated fibrosarcoma (RAF) inhibitors by activating PI3K/AKT signaling in melanoma cell lines and mouse xenograft models." (PMID 38835349, 2024). "Furthermore, the stemness factor forkhead box D3, which has previously been shown to mediate resistance to melanoma therapy, was found to directly repress VISTA transcript and protein expression in melanoma cells." (PMID 39482534, 2024). "Expression of the transcription factor, forkhead box D3 (FOXD3), in human melanoma cell lines, is induced during blockage of the BRAF/MEK/ERK pathway leading to upregulation of ERBB3 and activation of Akt signaling, which promotes melanoma progression." (PMID 34067095, 2021). "In BRAF mutant melanoma, inhibition of ERK1/2 induces FOXD3 and mediates RAF inhibitor resistance." (PMID 29295999, 2018). "Consistently, we find that knockdown of SOX10, the upstream regulator of FOXD3 also sensitizes mutant BRAF melanoma cells to Vemurafenib in vitro and in vivo, suggesting that SOX10 can protect melanoma cells against the acute cytotoxic effect of RAF inhibitors." (PMID 29295999, 2018). "At the initial stage of drug treatment, SOX10 may provide rapid protection on melanoma cells by upregulating pro-survival factors such as FOXD3, MITF, and SAMMSON and therefore is important for the survival of melanoma cells." (PMID 29295999, 2018). "This is supported by Abel and Aplin, who showed that FOXD3 does not regulate ERBB3 expression in BRAF wild-type melanoma cells, nor in melanocytes." (PMID 27391157, 2016). "Indeed, a modified FOXD3 protein, containing a transcription activation domain rather than a repressor domain, still repressed MITF transcription in melanoma cells." (PMID 25670789, 2015). "While this further emphasizes the close connection of the MAPK pathway with the regulation of MITF in melanoma cells, the role of SOX10 and FOXD3 in regulating MITF downstream of ERK under physiological conditions in melanocytes is so far unknown." (PMID 25818589, 2015). "Various transcriptional regulators have been postulated to be responsible for this effect such as increased binding of the positive factor FOXD3 in melanoma or decrease binding of the negative factor CTBP1 in thyroid cancer." (PMID 26208478, 2015). "FOXD3 was reported to inhibit MITF expression, and therefore might participate to the maintenance of the melanoma initiating cell phenotype." (PMID 25105565, 2014). "Similarly, inhibition of ATF2 transcription in human melanoma 1361 cells increased SOX10 and FOXD3 transcription, albeit, to a lesser degree (3- and 1.5-fold, respectively) compared with human melanocytes." (PMID 21203491, 2010). "Additionally, the stemness factor forkhead box D3 (FOXD3), previously identified as a mediator of melanoma therapy resistance, was shown to directly repress VISTA transcript and protein expression in melanoma cells." (PMID 41233805, 2025).